IL10 (interleukin 10)
Diseases named in the same sentence as IL10 in open-access papers (continued):
Sharing a sentence is not in itself a finding about the gene and the disease.
kidney damage (25 papers, 2009 to 2024). "As for the relationship between diabetic complications and IL-10 polymorphism, IL-10 −592 genotype frequency, and allele frequency are significantly different in the diabetic patients with nephropathy." (PMID 30873205, 2019). "Infected IL-10−/− mice show an increase in diagnostic markers of kidney damage and leukocyte trafficking to the lungs." (PMID 27557867, 2016). "A lower frequency of CG genotype polymorphism IL-10 -1082G/A, which is related to higher expression of this cytokine, was associated with nephropathy in DM2." (PMID 26770985, 2016). "Study of −592C/A polymorphism of IL-10 revealed positive significant association between CC carriers and nephropathy (P = 0.001) and study of −590C/T polymorphism of IL-4 revealed positive significant association between CT carriers and nephropathy (P < 0.001)." (PMID 26587547, 2015). "For GM-CSF and IL-10 the sign of the correlation coefficients was predominantly negative, indicating that higher levels of these two effectors were associated with lower levels of kidney damage." (PMID 19641609, 2009). "Next, we examined whether IL-10 was involved in miR-146b-controlled kidney damage caused by CFT073." (PMID 37909731, 2023). "As the results, the highest levels of IL-10 secretion by LPS-stimulated PP or MLN cells of AA-induced nephropathy mice with LcS." (PMID 39262432, 2024). "Supplementation of AA-induced nephropathy mice with LcS enhanced intestinal IL-10 productions and alleviated intestinal inflammation, suggesting a preventive role of dietary factors in AKI-related consequences." (PMID 39262432, 2024). "The most frequently mentioned in scientific studies on nephropathy was IL-10, occurring, inter alia, in DN, FSMGS, MN, AKI and IL-20 found in CKD and AKI." (PMID 35054831, 2022). "The prophylactic co-vaccination with D2/IL-10 reduced the expression of kidney damage observed by electron microscopy, direct immunofluorescence, and H & E, along with reduced level of anti-nRNP/Sm antibodies (P = 0.048)." (PMID 34705865, 2021). "Compared to mice with an intact IL-10 gene, mice with the dendritic cell deletion of IL-10 showed significantly worse kidney function and more severe histologic kidney damage." (PMID 32898157, 2020). "IL-10 attenuates inflammation by suppressing the neutrophil and monocyte activation, reduction in the activation of NF-κB, which all are involved in the kidney damage." (PMID 28491856, 2017). "IL-10 promoter variants and haplotypes (GTA and GTC) have predictive value in determining the susceptibility to nephropathy in Tunisian T2DM patients." (PMID 22028700, 2011). "Some studies have revealed elevated IL-10 levels in the sera of diabetic patients with nephropathy, and a positive correlation between IL-10 levels and albuminuria has been suggested to participate in the DN pathogenesis." (PMID 22028700, 2011). "The protective role of splenic IL-10 against nephropathy has been demonstrated by previous studies." (PMID 39262432, 2024). "Similarly, apigenin has been demonstrated to reduce IL-6, TNF-α, and IL-1β levels, and increase IL-10 levels in the kidneys or serum in doxorubicin-induced male nephropathy BALB/c mice or in furan-induced nephropathy mice." (PMID 36422572, 2022). "Furthermore, there was also an increase in key anti-inflammatory cytokine levels, such as IL-10 and IL-4 after AT, which is also essential to reduce kidney damage." (PMID 34621463, 2021). "As observed in the present study, increased NF-κB expression was accompanied by an increase in TNF-α and IL-1β expressions, and a decrease in IL-10, which is anti-inflammatory, suggestive of the involvement of inflammation in the pathogenesis of nephropathy in the untreated diabetic rats." (PMID 34198937, 2021). "This compensatory increase in IL-10 levels could also prolong the course of nephropathy in DM1 patients." (PMID 26770985, 2016).
kidney damage (continued). "Plasma IL-8, IL-10, IL-17, C-C motif chemokine ligand 20 (CCL20), TNF-α and GDF15 correlated with kidney damage assessed as the magnitude of proteinuria." (PMID 39188767, 2024). "The same model demonstrated renal expression of IP-10, IL-10, TNF-α, and TGF-β and a weak correlation with kidney damage." (PMID 26824356, 2016). "In the current study, significant increases were observed in serum AAP, LAP, PEPCK, GR, β2-MG, IgA, IgG, LZM, IL-10, and TNF-α concentration in birds exposed to OTA in the diet, indicating that OTA induced kidney damage, oxidative stress, immune response, and inflammation." (PMID 34769489, 2021). "INF-γ, TNF-α, IL6, and IL-10 plasma levels were higher in patients with CKD as compared to those without nephropathy (P = 0.001, P = 0.004, P = 0.016, and P = 0.030, resp)." (PMID 26770985, 2016). "In our study, patients with CKD presented higher levels of IL-10 than patients without nephropathy, which is in agreement with other study." (PMID 26770985, 2016). "While serum levels of IFN-γ, IL-2, IL-4, and IL-12 did not display a difference between experimental groups (data not shown), expression of IL-5, IL-6, TNF-α, IL-10, CXCL1, and IL-1β was elevated in the NZM2410/J mice displaying signs of severe kidney damage." (PMID 28491039, 2017).
non-Hodgkin lymphoma (25 papers, 2006 to 2025). Distinct from Hodgkin lymphoma both morphologically and biologically, non-Hodgkin lymphoma (NHL) is characterized by the absence of Reed-Sternberg cells, can occur at any age, and usually presents as a localized or generalized lymphadenopathy associated with fever and weight loss. "For example, some genotypes have been evidenced to be correlated with a decreased expression of IL-10 and a higher risk to develop prostate cancer or non-Hodgkin's lymphoma (Refs 214, 215)." (PMID 38186186, 2024). "A number of studies have evaluated the association between specific polymorphisms of IL-6 and IL-10 genes and the risk of non-Hodgkin lymphoma." (PMID 32046104, 2020). "Non-Hodgkin lymphoma has been linked to infection with Coxiella burnetii, potentially through overproduction of IL-10 during infection with C. burnetii." (PMID 28840502, 2018). "Polymorphisms in the interleukin (IL)-2 and IL-10 genes are known to be associated with susceptibility to different immune-dysregulated disorders and cancers such as non-Hodgkin lymphoma (NHL)." (PMID 28713071, 2018). "Furthermore, the anti-inflammatory cytokine IL-10 has been implicated in non-Hodgkin lymphoma risk." (PMID 40076681, 2025). "Other studies indicated an elevation of IL-10 in different haematological malignancies such as Hodgkin lymphoma and non-Hodgkin lymphoma (Refs 120, 121)." (PMID 38186186, 2024). "The tumour promoting roles of IL-10+ MDSCs are not limited to solid tumours, as IL-10-producing CD14+HLA-DR– MDSCs have also been observed in patients with non-Hodgkin’s lymphoma and negatively correlated with anti-tumoural NK cell abundance." (PMID 38464388, 2024). "IL-10, as IL-6, is a growth factor for non Hodgkin's lymphoma and is often correlated to a poor prognosis." (PMID 19956602, 2009). "The correlation between plasma IL-6 and IL-10 levels was also demonstrated in patients with non-Hodgkin's lymphoma and post-transplant lymphoproliferative disorder." (PMID 16995954, 2006). "In addition, plasma levels of CXCL13, IL-6 and IL-10 were potential markers for treatment outcomes and survival of patients with AIDS-associated non-Hodgkin lymphoma (NHL)." (PMID 33732259, 2021). "Serum IL-10 is also considered to be a negative prognostic indicator for the survival of patients with non-Hodgkin's lymphoma." (PMID 21269511, 2011). "However, in non-Hodgkin lymphoma (NHL), MDSCs act on NK cells through the immunosuppressive effect of IL-10 but not on T cells." (PMID 36978204, 2023). "Moreover, ATL patients display elevated IL-10 transcript levels contrary to normal T cells and high IL-10 serum level is an unfavorable prognostic factor among ATL patients as well as in HTLV-I negative Hodgkin and non-Hodgkin lymphomas and chronic lymphocytic leukemia." (PMID 23962110, 2013).
respiratory infections (25 papers, 2011 to 2025). "B cells are less well characterized than T cells as an IL-10 source during respiratory infection, but IL-10+ Bregs have been shown to limit pathogenic pulmonary Th1 and Th17 responses in a murine model of Pneumocystis infection." (PMID 30874596, 2019). "Greater mitogen-induced production of IL-I0 has been associated with a low risk of severe respiratory infections and deficient IL-10 was associated with greater viral load following in vivo challenge with rhinovirus." (PMID 21247809, 2011). "In a high-risk cohort, we have previously reported that the ratio of IL-10 and IL-5 was protective against the susceptibility to respiratory infections during infancy and early childhood." (PMID 23724228, 2011). "However, IL-10 has been associated with both beneficial and detrimental effects during respiratory infections." (PMID 32414154, 2020). "For example, IL-10 overexpression has been described as a risk factor for the development of refractory Mycoplasma pneumoniae pneumonia in children, suggesting a central role for this cytokine in the development of chronic cases of respiratory infections caused by mycoplasma." (PMID 38731294, 2024). "Other studies have demonstrated the immunomodulatory activity of B. clausii, reducing the expressions of IL-4, IFN-γ, IL-12, TGF-β and IL-10 in allergic children with recurrent respiratory infections." (PMID 39770518, 2024). "In C. trachomatis respiratory infection, IL-10 was reported to inhibit the priming and expansion of Th1 responses and contribute to the fibrotic reaction following infection." (PMID 36985179, 2023). "The role of IL-10 during respiratory infection, especially acute influenza appears to be contradictory." (PMID 33407470, 2021). "These genes are directly involved in innate immune sensing (TLR, MYD88, JAK/STAT), and inflammation (IL-6, IFN, TNF, IL-10, IL-22) which are two common host signaling pathways activated by bacteria and viruses during acute respiratory infections." (PMID 27532264, 2016). "Several studies reported that IL-10 has an important protective role in controlling immunopathology during respiratory infections and ALI." (PMID 25329163, 2014). "Inflammation may play a role in cardiovascular events after respiratory infection, and elevated IL-6 and IL-10 cytokine concentrations at hospital discharge have been associated with early cardiovascular mortality." (PMID 33602977, 2021). "Induction of IL-10+ CD8 T cells by CD4 T cell-derived IL-2 may thus act as further layer of buffering against damaging inflammation during respiratory infections." (PMID 31412088, 2019). "As a classical probiotic, Lactobacillus has been associated with respiratory infections, able to enhance the body’s resistance to Spn infections and avoid excessive inflammatory damage by promoting an increase in IgA cells in the intestine and airways and regulating TNF-α and IL-10 balance." (PMID 37547684, 2023). "As in respiratory infection, CD4+ T cells are a critical source of IL-10 during AAD." (PMID 30874596, 2019).
nasal polyps (24 papers, 2009 to 2024). "Therefore, the IL-10 overproduction may be caused by the inhibition of the mTOR signaling pathway, contributing to the balance of the Th1/Th2 network in cultured nasal polyps." (PMID 19250527, 2009). "In CRS, decrements in IL‐10 have been associated with particular phenotypes, especially CRS with nasal polyps." (PMID 36780897, 2023). "In new research from Brazil, the level of IL-10 protein in nasal polyps was found to be significantly lower than that in mucosa from the control group." (PMID 36003393, 2022). "IL-4, IL-7, IL-10, and IL-12 correlate with Ki-67, which suggests the possible involvement of these cytokines in tissue cell proliferation in the case of recurrent nasal polyps." (PMID 36285981, 2022). "IL-1α, IL-6, IL-8, IL-10, IL-12 (p < 0.001), and IL-4 (p = 0.038) were increased in the subepithelial connective tissue of the nasal polyp samples when compared to the control samples." (PMID 36285981, 2022). "Secondary CRSwNP showed the same Ki-67 correlations with an additional correlation with IL-10 in the case of recurrent nasal polyps." (PMID 36285981, 2022). "IL-1α, IL-4, IL-6, IL-8, IL-10, IL-12 (p < 0.001), and Ki-67 (p = 0.001) were decreased in the epithelium of the nasal polyp samples in comparison to the control samples." (PMID 36285981, 2022). "When comparing nasal polyp samples with normal mucosa from control patients, it was apparent that IL-1α, IL-4, IL-6, IL-7, IL-8, IL-10, IL-12 positive structures were significantly decreased in epithelium of the polyps." (PMID 34208325, 2021). "In the context of N-ERD, Stevens showed that IL-10 is decreased in nasal polyps from patients with this disease in comparison to patients with CRSwNP, on another hand in an epigenetic study Cheong reported that IL10 gene is susceptible to hypomethylation." (PMID 31936183, 2020). "In this study, we investigated IL-10 expression in chronic rhinosinusitis with nasal polyps (CRSwNP) and assessed the possible role of IL-10 in the pathogenesis of CRSwNP." (PMID 27584662, 2016). "HPV-11 positive SNP-WoAD patients presented with mHLA-G and IL-10R on epithelial cells from nasal polyps and showed secretion of sHLA-G and IL-10 in culture supernatants." (PMID 24741599, 2014). "In conclusion, this is the first study elucidating the possible involvement of IL-10/HLA-G feedback loop in maintaining HPV infection in nasal polyps from SNP-WoAD patients." (PMID 24741599, 2014). "The infiltration of inflammatory cells, particularly eosinophils (EOSs) and T lymphocytes, and abnormalities in the cytokines, including the upregulation of interleukin (IL)-4, IL-5 and IL-10, are characteristics of the immune dysfunction of nasal polyps." (PMID 23737902, 2013). "In the tissue culture system, we detected significantly elevated Foxp3 expression and IL-10 production, as well as an increased percentage of Foxp3+ Tregs in nasal polyps after blocking the mTOR signaling pathway with rapamycin." (PMID 19250527, 2009). "The relationship of IL-17 and IL-10 with nasal polyp has also been reported." (PMID 35145935, 2022). "Thus, it is possible that IFN-α, by increasing the concentration of IL-10 in eosinophilic nasal polyp cell cultures, modulates a regulatory action on the eosinophilic inflammatory process." (PMID 31870738, 2021). "IL-10 detection is necessary for evaluation of anti-inflammatory responses in nasal polyps." (PMID 34208325, 2021). "Therefore, our aim is to investigate the complex appearance, relative distribution and interlinks of IL-1, IL-4, IL-6, IL-7, IL-8, IL-10, IL-12 and Ki 67 in chronic rhinosinusitis with nasal polyps (CRSwNP) affected human nasal mucosa." (PMID 34208325, 2021). "Epithelial IL-10 was significantly decreased in nasal polyps when compared to controls." (PMID 34208325, 2021).
nasal polyps (continued). "To test the hypothesis, we collected peripheral DCs from patients with nasal polyp and found that the expression of IL-10 in peripheral DCs was compromised, which was negatively correlated with the increase in miR-19a in DCs." (PMID 28388587, 2017). "We conclude that miR-19a plays a critical role in the suppression of IL-10 in peripheral DCs, which may be a target in the immune therapy for nasal polyp." (PMID 28388587, 2017). "In addition, a negative correlation was identified between the expression of IL-10 and miR-19a in DCs in patients with nasal polyps." (PMID 28388587, 2017). "The present data show that miR-19a may one of the factors to inhibit the expression of IL-10 in DCs of patients with nasal allergy and nasal polyp." (PMID 28388587, 2017). "The present data show a previously unknown phenomenon that peripheral DCs in patients with nasal polyp and nasal allergy express high levels of miR-19a and low levels of IL-10." (PMID 28388587, 2017). "The present data provide a possible hint that the increase in miR-19a and decrease in IL-10 in peripheral DCs in patients with nasal polyp may play a role in the development of nasal polyp." (PMID 28388587, 2017). "The number of IL-10 positive structures was noted with abundant (++++) cells in the epithelium and moderate (++) cells in the connective tissue of the control samples, and few (+) cells in the epithelium and moderate-to-numerous (++/+++) cells in the connective tissue of the nasal polyp samples." (PMID 36285981, 2022). "Decrease of IL-6 in both—epithelium and connective tissue with strong correlation between it and IL-7 and IL-10 in connective tissue suggests significant stimulation of this regulatory cytokine and, possibly, the important role in pathogenesis of the development in nasal polyps." (PMID 34208325, 2021). "However, scholars have demonstrated that IL-10 is highly expressed in nasal polyp tissues." (PMID 23737902, 2013). "IL‐10+ GZMK+ CD4+ T cells have primarily been described in tumours, as well as nasal polyps from chronic rhinosinusitis patients." (PMID 38707998, 2024). "Our aim was to use detected IL-1, IL-4, IL-6, IL-7, IL-8, IL-10, IL-12, Ki 67, HBD-2, HBD-3, and LL-37 to classify specific inflammatory endotypes in chronic rhinosinusitis with the tissue of nasal polyps (CRSwNP)." (PMID 38791197, 2024). "Therefore, our aim was to use detected IL-1, IL-4, IL-6, IL-7, IL-8, IL-10, IL-12, Ki 67, HBD-2, HBD-3, and LL-37 to classify specific inflammatory endotypes in chronic rhinosinusitis with the tissue of nasal polyps (CRSwNP)." (PMID 38791197, 2024). "IL-5, IL-6, and IL-10 levels were significantly increased in asthmatic patients with nasal polyps compared with non-asthmatic patients with nasal polyps." (PMID 29564208, 2018). "Nasal polyp tissues showed significantly (P ≤ 0.01) altered gene expression values for over 4,000 genes and a significant increase of Th2 cytokines (IL-4, IL-5, IL-10, and IL-13) compared to the inferior turbinate (data not shown)." (PMID 24995349, 2014). "Indeed, the effect of IL-4/IL-13 and IL-5 on nasal epithelial repair was already showed but to date, no study has precisely described the role of IL-6, IL-9 and IL-10 (new ILs described in nasal polyposis) on human nasal epithelial cells in an in vitro wound repair model." (PMID 32209102, 2020). "After 48 and 72 h of infection with herpes simplex virus 1 (HSV1), a type of RSV, a significantly higher level of released IL-10, rather than IFN-λ, was detected in the supernatant of nasal polyps compared to control mucosa." (PMID 36003393, 2022). "Polycytidylic acid (poly (IC)) is the ligand for TLR3, and exposure to poly (IC) selectively induces IL-10, but not IL-5, IL-13, IFN-γ or IL-17A, production by nasal polyp cells." (PMID 36003393, 2022).
nasal polyps (continued). "The high IL-10 in the absence of an antigenic stimulus (post FESS and removal of the nasal polyp) may have a beneficial role by suppression of Th17 signals, thus enabling tissue repair, as explained in previous studies." (PMID 33238997, 2020). "However when treating single cell suspensionsof nasal polyp sampleswith SEBfor 24 hours, we demonstrated that SEB induces anup-regulation of T cells secreting IL-10, whereas Tcells expressing other cytokines were not increasing in numbers." (PMID 24911279, 2014).